PLTP (phospholipid transfer protein)
Description:
Mediates the transfer of phospholipids and free cholesterol from triglyceride-rich lipoproteins (low density lipoproteins or LDL and very low density lipoproteins or VLDL) into high-density lipoproteins (HDL) as well as the exchange of phospholipids between triglyceride-rich lipoproteins themselves. Facilitates the transfer of a spectrum of different lipid molecules, including diacylglycerol, phosphatidic acid, sphingomyelin, phosphatidylcholine, phosphatidylinositol, phosphatidylglycerol, cerebroside and phosphatidyl ethanolamine. Plays an important role in HDL remodeling which involves modulating the size and composition of HDL. Also plays a key role in the uptake of cholesterol from peripheral cells and tissues that is subsequently transported to the liver for degradation and excretion. Two distinct forms of PLTP exist in plasma: an active form that can transfer phosphatidylcholine from phospholipid vesicles to HDL, and an inactive form that lacks this capability.
Synonyms: BPIFE; HDLCQ9
Tractability: Antibody: UniProt places it where antibodies can reach, with high confidence; its Gene Ontology location is reachable by antibodies, with high confidence; UniProt predicts a signal peptide or a membrane-spanning region. PROTAC: ubiquitination databases record sites on it; its protein half-life has been measured; a small molecule that binds it is known.
Target class: Ion channel; Other ion channel; Pore-forming toxins (proteins and peptides)
Gene: Protein-coding gene on chromosome 20 (45,898,621 to 45,912,235, reverse strand). Ensembl gene ENSG00000100979.
Subcellular location: Secreted; Nucleus
Pathways (Reactome):
Signal Transduction: NR1H3 & NR1H2 regulate gene expression linked to cholesterol transport and efflux
Transport of small molecules: HDL remodeling
Gene Ontology:
Molecular function: ceramide binding; cerebroside transfer activity; diacylglyceride transfer activity; diacylglycerol binding; high-density lipoprotein particle binding; low-density lipoprotein particle binding; phosphatidic acid binding; phosphatidic acid transfer activity; phosphatidylcholine binding; phosphatidylcholine transfer activity; phosphatidylethanolamine binding; phosphatidylethanolamine transfer activity; phosphatidylglycerol binding; phosphatidylglycerol transfer activity; phospholipid transfer activity; sphingomyelin transfer activity; very-low-density lipoprotein particle binding; ceramide transfer activity; cholesterol transfer activity; phosphatidylinositol transfer activity; lipid binding
Biological process: ceramide transport; glycolipid transport; high-density lipoprotein particle remodeling; lipid transport; phospholipid transport; positive regulation of cholesterol efflux; lipid metabolic process; intermembrane lipid transfer; sterol transport
Cellular component: extracellular region; high-density lipoprotein particle; nucleus
Genetic constraint (gnomAD): Loss-of-function variants: 44 observed, 56.43 expected, observed/expected ratio (o/e) 0.78, 90% interval 0.61 to 1. The upper end of that interval is the gene's LOEUF score, 1, which puts it in group 4 of 6, group 1 being the genes least tolerant of losing a copy. Missense variants: 603 observed, 665.71 expected, observed/expected ratio (o/e) 0.91, 90% interval 0.85 to 0.97. Synonymous variants: 263 observed, 275.9 expected, observed/expected ratio (o/e) 0.95, 90% interval 0.86 to 1.06.
Homologues: Orthologues: macaque PLTP (98% identical), chimpanzee PLTP (95% identical), dog PLTP (94% identical), rabbit PLTP (87% identical), guinea pig PLTP (83% identical), mouse Pltp (82% identical), rat Pltp (82% identical), tropical clawed frog pltp (61% identical), zebrafish pltp (53% identical), Caenorhabditis elegans C06E8.5 (17% identical). Paralogues in human: BPI (25% identical), BPIFC (23% identical), LBP (23% identical), CETP (18% identical), BPIFB3 (17% identical), BPIFB4 (16% identical), BPIFB2 (16% identical), BPIFB1 (15% identical), BPIFB6 (14% identical), BPIFA1 (8% identical), BPIFA3 (8% identical), BPIFA2 (6% identical).
Diseases named in the same sentence as PLTP in open-access papers:
PLTP is named in the same sentence as 104 diseases in open-access papers, as found by Europe PMC text mining. Sharing a sentence is not in itself a finding about the gene and the disease. The quoted sentences say what the papers report.
atherosclerosis (41 papers, 2008 to 2026). A disease characterized by the build-up of fatty material and calcium deposition in the arterial wall resulting in partial or complete occlusion of the arterial lumen. "Altered PLTP activity has been linked to atherosclerosis, cardiovascular disease, and inflammatory pathways, underscoring its relevance to cardiac pathophysiology." (PMID 42074254, 2026). "Phospholipid transfer protein (PLTP), a key player in lipoprotein conversion and metabolism, has been positively linked to the risk of cardiovascular diseases, including atherosclerosis." (PMID 40444232, 2025). "PLTP, meanwhile, is well-established in atherosclerosis – a disease sharing AD’s chronic inflammatory hallmark – where it regulates lipid transport and macrophage foam cell formation, indirectly promoting inflammatory mediator release and vascular wall injury." (PMID 41305697, 2025). "In mouse models, PLTP deficiency reduces atherosclerosis, while its overexpression shows the opposite effect." (PMID 39343001, 2024). "PLTP, the increased activity of which is known to be associated with atherosclerosis, systolic dysfunction, obesity, and diabetes (Chowaniec and Skoczyńska, 2018), was observed to be suppressed explicitly in all three IF groups." (PMID 37769126, 2023). "PLTP has been extensively characterized in the context of atherosclerosis and studies have shown that low levels of PLTP are associated with greater risk of atherosclerosis." (PMID 36309086, 2022). "In human studies, both PLTP mass and PLTPa were associated with plasma lipid traits, glucose regulation, and atherosclerosis." (PMID 34385888, 2021). "PLTP-deficiency in mice is associated with a decreased susceptibility to atherosclerosis despite decreased HDL." (PMID 29565987, 2018). "In mouse models, it has been demonstrated that PLTP overexpression induces atherosclerosis, while its deficiency reduces it." (PMID 22897926, 2012). "In mouse models, it has been demonstrated that PLTP overexpression induces atherosclerosis, while its deficiency shows the opposite effect." (PMID 22897926, 2012). "Lastly, discovery of humans with genetic PLTP deficiency would be a major step toward the elucidation of the role of this transfer protein in human lipoprotein metabolism and atherosclerosis." (PMID 22897926, 2012). "PLTP synthesized by macrophage and MFCs has been associated with the development of atherosclerosis." (PMID 20534134, 2010). "On the contrary, PLTP deficiency results in markedly decreased atherosclerosis by a decrease in the production and levels of apoB-containing lipoprotein, an increase in their vitamin E content, and a decrease in their susceptibility to oxidation." (PMID 20937151, 2010). "Although the mechanism of these associations remains poorly defined, it is likely related to the putative role of PLTP in the development of atherosclerosis, a common underlying factor in each of these disease states." (PMID 19948027, 2009). "PLTP is involved in the pathogenesis of atherosclerosis which causes coronary artery disease, the leading cause of death in North America." (PMID 19627602, 2009). "Recently, the susceptibility to diet-induced atherosclerosis was studied in mice after bone marrow transplantations with bone marrow cells from wild type and PLTP deficient mice." (PMID 18509527, 2008). "Experimental evidence suggests the cardioprotective role of APOB in enhancing survival and cardiac function post-MI, while numerous basic research studies have implicated PLTP in the development of atherosclerosis, with clinical studies broadly confirming its pro-atherogenic role as well." (PMID 39513871, 2024). "In mouse models, PLTP overexpression induces atherosclerosis, while its deficiency reduces it." (PMID 36309086, 2022). "Previous studies have suggested that PLTP increases the risk of cardiovascular disease in humans, and the balance of evidence suggests a pro-atherogenic role for oxLDL Ab titers in the development of atherosclerosis." (PMID 23039379, 2012).
atherosclerosis (continued). "In general, elevation of systemic PLTP is a risk factor for atherosclerosis in animal models." (PMID 22897926, 2012). "Accordingly, PLTP has been implicated in the development of atherosclerosis." (PMID 19948027, 2009). "In humans, the causal relation between PLTP and atherosclerosis is still uncertain." (PMID 18509527, 2008). "In mouse models used to study psoriasis, which is induced by imiquimod, elevated levels of phospholipid transfer protein (PLTP) and cholesterol ester transfer protein (CETP) exacerbate the condition and increase the risk of atherosclerosis." (PMID 39712184, 2024). "Therefore, Cd exposure can be a risk factor for multi-tissular steatosis, atherosclerosis, and metabolic dyslipidemia associated with defects in the enzymatic activity of cholesterol ester transfer protein, lecithin-cholesterol acyltransferase, and phospholipid transfer protein (PLTP)." (PMID 36976988, 2023). "CETP-Tg and PLTP-Tg mice have significantly low HDL levels and a high risk of developing atherosclerosis." (PMID 35982498, 2022). "In mouse models, PLTP deficiency reduces VLDL and LDL levels and attenuates atherosclerosis, while PLTP overexpression exerts an opposite effect." (PMID 36140167, 2022). "Higher PLTP expression within transgenic (Tg) mice accelerates atherosclerosis (AS) and decreases HDL." (PMID 35982498, 2022). "Several previous studies have found that PLTP is an emerging cardiac metabolic factor which exerts a vital part in the development of blood lipid metabolism and atherosclerosis." (PMID 34385888, 2021). "Intriguingly, among these secreted proteins, PLTP, CD5L, and LPL have been reported to exacerbate or be associated with advanced atherosclerosis, whereas IL18BP is anti‐atherogenic." (PMID 33231376, 2021). "Although plasma phospholipid transfer protein (PLTP) has been mainly studied in the context of atherosclerosis, it shares homology with proteins involved in innate immunity." (PMID 28596518, 2017). "Because PLTP mediates the transfer of a spectrum of plasma lipids and the antioxidant tocopherol on lipoproteins, PLTP was first found to be involved in lipid homeostasis and also in atherosclerosis." (PMID 28848554, 2017). "Further, more epidemiological studies are needed to gain insights into the role of PLTP in atherosclerosis." (PMID 22897926, 2012). "phospholipid transfer protein (PLTP) plays important roles in lipoprotein metabolism and atherosclerosis and is expressed by macrophages and macrophage foam cells (MFCs)." (PMID 20534134, 2010). "PLTP has been already identified like one of the "candidate genes" for atherosclerosis and this is confirmed by our meta-analysis." (PMID 19134193, 2009). "There is evidence that even a 10% reduction on PLTP activity can lead to a significant reduction of atherosclerosis progression, highlighting the role of PLTP on the development of cardiovascular disease." (PMID 19627602, 2009). "In fact, we have shown in a previous study that in animals with elevated PLTP activity, both males and females have more atherosclerosis." (PMID 18509527, 2008). "Their results are in line with our findings, as we report an increase of atherosclerosis in mice transplanted with PLTP overexpressing bone marrow, while they found decreased atherosclerosis in mice transplanted with PLTP−/− bone marrow cells." (PMID 18509527, 2008). "In contrast, we observed a clear PLTP-dose dependent reduction of plasma HDL levels in parallel to the induction of atherosclerosis and therefore we concluded that elevated plasma PLTP activity in transgenic mice is atherogenic because it decreases plasma HDL." (PMID 18509527, 2008). "In order to find out what the contribution of PLTP expressing macrophages to diet induced atherosclerosis would be, we performed bone marrow transplantation experiments." (PMID 18509527, 2008). "In conclusion, we showed that elevated macrophage expression of PLTP results in increased atherosclerosis." (PMID 18509527, 2008).
atherosclerosis (continued). "It is conceivable that increased PLTP activity in choroidal macrophages could favor lipid accumulation in adjacent tissues similar to that seen in atherosclerosis, leading to the formation of lipid-rich drusen beneath the RPE." (PMID 40196652, 2025). "The relationship of PLTP to atherosclerosis is rather puzzling and may be dependent on the experimental setting, the animal model used and the PLTP source (plasma versus macrophage-derived)." (PMID 29731975, 2018). "This could possibly explain why some studies suggested a protective role of PLTP, in atherosclerosis, for example when PLTP is expressed in macrophages or in the context of endotoxemia." (PMID 29565987, 2018). "In addition to its role in lipoprotein metabolism and atherosclerosis, the latest advances came in support of a complex role of PLTP in the regulation of the inflammatory response, both with pro-inflammatory or anti-inflammatory properties." (PMID 29565987, 2018). "PLTP is considered a promising target for pharmacological intervention to treat atherosclerosis." (PMID 22897926, 2012). "It is reported that CETP and PLTP activities are closely related to atherosclerosis (AS)." (PMID 20937151, 2010). "Although our findings need to be confirmed in additional studies, they hold the promise that PLTP might be therapeutic target for the treatment of atherosclerosis." (PMID 19948027, 2009). "There is increasing evidence supporting the role of PLTP on atherosclerosis development." (PMID 19627602, 2009). "Haptoglobin, HDL and PLTP activity correlation data suggests the potential to use haptoglobin as a biomarker for the development of atherosclerosis as well as a tool to understand the role of PLTP activity and haptoglobin levels in reverse cholesterol and atherosclerosis." (PMID 19627602, 2009). "Indeed, we provided further evidence of an atherogenic role of PLTP in studies in a series of PLTP transgenic mouse lines with increasing levels of plasma PLTP activity, showing a PLTP-dose dependent enhancement of atherosclerosis." (PMID 18509527, 2008). "Therefore, it was suggested that PLTP has a role in the development of atherosclerosis, based on its relation with HDL function." (PMID 18509527, 2008). "In order to investigate the mechanism by which mice transplanted with bone marrow cells expressing elevated levels of PLTP develop more atherosclerosis, we performed a series of in vitro studies using primary macrophages from PLTPwt/wt, huPLTPtg/wt, and huPLTPtg/tg mice, respectively." (PMID 18509527, 2008). "Pltp (phospholipid transfer protein), a monomeric protein that belongs to a family of lipid transfer/lipopolysaccharide-binding proteins, involves in lipoprotein metabolism, cardiovascular diseases, and atherosclerosis, as well as obesity and insulin resistance." (PMID 36312255, 2022). "Finally, mice deficient in phospholipid transfer protein (PLTP), a protein known to correlate with atherosclerosis severity, showed reduced levels of RIPK3 in atherosclerotic plaques in addition to reduced atherosclerotic lesion burden and intra-lesion cell death." (PMID 33142926, 2020). "Loss of function mutations in ANGPTL4 and genetic variations in PLTP that attenuate its plasma activity have been associated with an attenuated risk of coronary artery disease, emphasizing the relevance of ANGTP4- and PLTP-mediated processes on the development of atherosclerosis." (PMID 29587751, 2018). "Additionally, it is well established that overexpression of PLTP increases atherosclerosis and decreased expression, depending on the pathophysiological context, may protect against atherosclerosis as found in this study." (PMID 30219096, 2018).
atherosclerosis (continued). "Elevated levels of total cholesterol, PLTP, RANTES, IL-6, insulin and leptin, which showed correlation with 18F-FMCH uptake, have been linked with increased atherosclerosis thus lending support to the association between 18F-FMCH uptake and the risk of atherosclerosis." (PMID 26852231, 2016). "Importantly, PLTP clearly has a notable role in the development of atherosclerosis." (PMID 22897926, 2012). "RCT is considered to be the primary mechanism through which HDL protects against atherosclerosis, but its production is limited in LAD patients by LPL down-regulation and PLTP up-regulation." (PMID 19134193, 2009). "The overexpression of PLTP resulted in a significant decrease of plasma levels of HDL-C, increase the formation of preβ-HDL, increase catabolism HDL, increased atherosclerosis, compared with plasma from WT mice." (PMID 19948027, 2009). "In genetically modified mouse models the relation between the activity levels of PLTP in plasma, HDL levels, HDL subclass distribution and the development of atherosclerosis was studied in more detail." (PMID 18509527, 2008). "These PLTP KO mice also have significantly lower levels of HDL cholesterol found in the plasma, due to impaired cholesterol absorption in the intestine, and they show decreased atherosclerosis." (PMID 36309086, 2022). "Unlike LBP and BPI, phospholipid transfer protein (PLTP) has been initially mainly studied in the context of lipid transport, atherosclerosis, and cardiovascular diseases." (PMID 33500240, 2021). "Elevated levels of PLTP in transgenic mice result in decreased HDL and increased atherosclerosis." (PMID 18509527, 2008). "Although intriguing, the presence of PLTP in atherosclerotic lesions per se does not prove a direct involvement in the process of atherosclerosis and therefore the significance of these findings is unclear." (PMID 18509527, 2008). "In agreement with previous studies from our laboratory, we found that elevated levels of PLTP result in a strong increase (312%) in diet-induced atherosclerosis in non-transplanted mice (p<0.001)." (PMID 18509527, 2008). "PLTP promotes phosphatidylserine externalization on the platelet plasma membrane and accelerates adenosine diphosphate (ADP) or collagen-induced platelet aggregation, and its altered expression may influence atherosclerosis." (PMID 36959823, 2023). "Although underexpression of PLTP has not yielded conclusive results in animal models, other functions have been recognized in vascular compartment lipid transport, impacting diseases such as atherosclerosis, cancer, and neurodegenerative disease." (PMID 35625159, 2022).